SNORD64 (small nucleolar RNA, C/D box 64)
Synonyms: HBII-13
Gene: Small nucleolar RNA gene on chromosome 15 (24,985,100 to 24,985,166, forward strand). Ensembl gene ENSG00000276610.
Gene Ontology:
Biological process: RNA processing
Cellular component: nucleolus
Homologues: Orthologues: chimpanzee SNORD64 (100% identical), macaque SNORD64 (99% identical), rabbit SNORD64 (88% identical), mouse Snord64 (87% identical), rat Snord64 (85% identical), guinea pig SNORD64 (78% identical), dog SNORD64 (75% identical).
Diseases named in the same sentence as SNORD64 in open-access papers:
SNORD64 is named in the same sentence as 2 diseases in open-access papers, as found by Europe PMC text mining. Sharing a sentence is not in itself a finding about the gene and the disease.
SNORD64 shares sentences with these, for which no sentence is quoted: leukemia (1 paper); morbid obesity (1).